INSL6 (insulin like 6)
Description:
May have a role in sperm development and fertilization.
Synonyms: RIF1
Tractability: Antibody: UniProt places it where antibodies can reach, with medium confidence; UniProt predicts a signal peptide or a membrane-spanning region; its Gene Ontology location is reachable by antibodies, with medium confidence.
Gene: Protein-coding gene on chromosome 9 (5,123,880 to 5,185,647, reverse strand). Ensembl gene ENSG00000120210.
Subcellular location: Secreted
Gene Ontology:
Molecular function: hormone activity
Biological process: signal transduction
Cellular component: extracellular region
Genetic constraint (gnomAD): Loss-of-function variants: 17 observed, 10.56 expected, observed/expected ratio (o/e) 1.61, 90% interval 1.07 to 1.94. The synonymous counts are far from expectation, so gnomAD's model fits this gene poorly and the ratio says little. Missense variants: 379 observed, 260.56 expected, observed/expected ratio (o/e) 1.45, 90% interval 1.34 to 1.58. Synonymous variants: 152 observed, 98.97 expected, observed/expected ratio (o/e) 1.54, 90% interval 1.35 to 1.76.
Homologues: Orthologues: chimpanzee INSL6 (96% identical), macaque INSL6 (89% identical), dog INSL6 (64% identical), rabbit INSL6 (64% identical), pig INSL6 (62% identical), guinea pig INSL6 (53% identical), rat Insl6 (42% identical), mouse Insl6 (42% identical). Paralogues in human: RLN1 (22% identical), RLN2 (21% identical), INSL4 (10% identical).
Diseases named in the same sentence as INSL6 in open-access papers:
INSL6 is named in the same sentence as 19 diseases in open-access papers, as found by Europe PMC text mining. Sharing a sentence is not in itself a finding about the gene and the disease. The quoted sentences say what the papers report.
myositis (3 papers, 2014 to 2023). "The consequences of Insl6-deficiency were evaluated in a murine model of myositis, where a recombinant fragment of human fast-type skeletal myosin-binding C protein was used as antigen in wild-type C57BL/6 female mice." (PMID 25161767, 2014). "Insl6-deficiency in mice led to a worsened myositis phenotype including increased infiltration of CD4 and CD8 T cells and the elevated expression of inflammatory cytokines." (PMID 25161767, 2014). "Based on an experimental model of autoimmune myositis (EAM), induced in mice with human myosin-binding protein C, deficiency in Insl6 resulted in a worsened myositis phenotype with infiltration of CD4 and CD8 T-cells as well with an increased expression of inflammatory cytokines." (PMID 32775472, 2020). "The improvement in myositis by Insl6 could also be demonstrated by acute hydrodynamic delivery of a plasmid encoding murine Insl6." (PMID 25161767, 2014). "Muscle-specific Insl6 overexpression protects the muscle against the development of myositis and results in reduced lymphocyte infiltration in muscle tissue, decreased expression of inflammatory cytokines, and an improvement in motor function." (PMID 32775472, 2020). "We have seen that some of myokines, as follistatin and Insl6, have a low expression in myositis, intense exercise being already a good modulator, so as to induce their overexpression for the benefit of muscle tissue." (PMID 32775472, 2020). "Insulin-like 6 (Insl6) is a myokine recently approached in myositis studies, being a member of insulin-like/relaxin family." (PMID 32775472, 2020). "We therefore sought to extend these studies and explore the utility of Insl6 in the setting of inflammatory muscle injury using a rodent model of myositis." (PMID 25161767, 2014). "Alterations in Insl6 expression in samples taken from both human and murine myositis-affected muscle highlight the potential for translational impact." (PMID 25161767, 2014). "Conversely, muscle-specific overexpression of Insl6 protected against the development of myositis as indicated by reduced lymphocyte infiltration in muscle, diminished inflammatory cytokine expression and improved motor function." (PMID 25161767, 2014). "Deficiency of Insl6 led to an increase in CD4 and CD8 T cell infiltration, increased inflammatory cytokine expression and greater motor function impairment in the myositis model." (PMID 25161767, 2014). "Interestingly, Insl6 mRNA transcript levels are down-regulated in human myositis biopsy samples, whereas this factor is upregulated in the murine models of myositis and cardiotoxin injury." (PMID 25161767, 2014). "Whereas transcript levels of Insl6 in control muscle were fairly uniform, myositis patients displayed an overall reduction in Insl6 transcript levels (P = 0.0378) and the expression of Insl6 was more heterogeneous with some patients exhibiting very low levels of this factor." (PMID 25161767, 2014). "To test whether the acute expression of Insl6 is protective in the myositis model, we employed a hydrodynamic model of Insl6 gene delivery." (PMID 25161767, 2014). "The authors of this study suggested that Insl6 could become a target for the treatment of myositis." (PMID 32775472, 2020). "Thus, reestablishing the normal upregulation of Insl6 in muscle of myositis patients may have therapeutic utility." (PMID 25161767, 2014).
Obesity (2 papers, 2016 to 2025). Accumulation of substantial excess body fat. "The genes found to be positively selected in Enshi pigs are involved in crucial biological processes such as body size and immunity (RPS10 and VASN), obesity (GSK3), male fertility (INSL6), and early development (TBX19)." (PMID 27808243, 2016).
autoimmune disease (1 paper, 2014). A disorder resulting from loss of function or tissue destruction of an organ or multiple organs, arising from humoral or cellular immune responses of the individual to their own tissue constituents. "However, in chronic human disease, the reduction of Insl6 by an as-yet-unidentified mechanism may contribute to the development of idiopathic inflammatory myopathies or other autoimmune diseases." (PMID 25161767, 2014).
breast carcinoma (1 paper, 2023). "INSL6 expression was downregulated in the MI group, and overall survival analysis demonstrated that INSL6 could be the prognostic biomarkers in the overall survival of breast cancer (BRCA)." (PMID 36798786, 2023).
dermatomyositis (1 paper, 2014). Dermatomyositis (DM) is a type of idiopathic inflammatory myopathy characterized by evocative skin lesions and symmetrical proximal muscle weakness. "Insl6 transcript expression in muscle was reduced in a cohort of dermatomyositis and polymyositis patients." (PMID 25161767, 2014). "The mRNA transcript level of Insl6 was assessed in human skeletal muscle biopsy samples from polymyositis and dermatomyositis patients." (PMID 25161767, 2014).
developmental delay (1 paper, 2025). "Chromosomal microarray showed a duplication on 9p, arr[hg19] 9p24.1 (5108833-5221708) × 3, that included the JAK2 and INSL6 genes, classified as a variant of uncertain significance and not thought to be related to the patient’s developmental delay." (PMID 40869981, 2025).
infiltrating ductal carcinoma (1 paper, 2023). "Overall survival analysis of subgroups in BRCA was also carried out, which demonstrated that lower INSL6 expression had a worse prognosis in white patients as well as patients with N0, M0, negative ER status, infiltrating ductal carcinoma, or LumB." (PMID 36798786, 2023).
male fertility (1 paper, 2023). A fertility quality of inhering in a male by virtue of the bearer's disposition to initiate, sustain, or support reproduction. "INSL6 levels have been found to correlate positively with male fertility in humans." (PMID 37691832, 2023).
myocardial infarction (1 paper, 2023). Gross necrosis of the myocardium, as a result of interruption of the blood supply to the area, as in coronary thrombosis. "INSL6 is differentially expressed after myocardial infarction and also in a variety of tumors and aberrant expression is associated with the progression and immune cell infiltration of the tumor, especially in KIRP and BRCA." (PMID 36798786, 2023).
spermatogenic failure (1 paper, 2023). A male infertility characterized by dirsuption of the process of sperm development from diploid cells into mature haploid spermatozoa. "R171H missense mutation of INSL6 could lead to a patient with spermatogenic failure (, e455)." (PMID 36798786, 2023).
cancer (2 papers, 2007 to 2023). A tumor composed of atypical neoplastic, often pleomorphic cells that invade other tissues. "INSL6 might be a potential diagnostic and prognostic biomarker of cancers due to the high accuracy in diagnostic and prognostic value." (PMID 36798786, 2023). "INSL6 expression differs significantly not only in most cancers but also in different molecular and immune subtypes of cancers." (PMID 36798786, 2023). "As in the cancer cell lines, we observed promoter hypomethylation in the primary tumors; the frequency of hypomethylation was 5% (1/20) for ANKRD30A, 20% (4/20) for FLJ40201, 0% (0/20) for INSL6, 30% (6/20) for SOHLH2, 20% (4/20) for FTMT, 25% (5/20) for C12orf12, and 30% (6/20) for DPPA5." (PMID 17967063, 2007).
inflammatory myopathy (1 paper, 2014). "The present study also reports that Insl6 is protective in a murine model resembling human inflammatory myopathy using genetically modified mice either lacking or overexpressing Insl6." (PMID 25161767, 2014).
tumor (1 paper, 2023). "Therefore, INSL6 aberrant expression is associated with the progression and immune cell infiltration of the tumor, especially in KIRP and BRCA." (PMID 36798786, 2023). "INSL6 expression may be the crosstalk between MI and BRCA due to their high diagnostic and prognostic value as well as the methylation effects on BRCA tumor environments." (PMID 36798786, 2023). "Therefore, INSL6 may serve as a potential prognostic biomarker and the crosstalk between MI and tumor progression." (PMID 36798786, 2023). "Hypothetically, INSL6 expression was downregulated in the FAMI A and FAMI B group, which may impede the inhibitions on tumor progression." (PMID 36798786, 2023). "Compared to control, INSL6 expression was downregulated in FAMI A and FAMI B groups, which may impede the inhibitions on tumor progression." (PMID 36798786, 2023). "Compared to control, INSL6 expression was downregulated in the FAMI A and FAMI B group, which may impede the inhibitions on tumor progression." (PMID 36798786, 2023).
INSL6 also shares sentences with these, for which no sentence is quoted: cardiovascular diseases (1 paper); Infertility (1); male infertility (1); ovarian tumors (1); polymyositis (1); rheumatoid arthritis (1).